CD207 (CD207 molecule)
Diseases named in the same sentence as CD207 in open-access papers (continued):
Sharing a sentence is not in itself a finding about the gene and the disease.
oral cancer (1 paper, 2020). "Our study investigated the distribution profile of the DCs in OSMF, OSMF-OSCC, OL, and OSCC and revealed a significant decrease of CD1a+ and CD207+ cells in oral cancer and OSMF, but not for CD303 positive cells." (PMID 31880289, 2020).
periodontitis (1 paper, 2025). An acute or chronic inflammatory process that affects the tissues that surround and support the teeth. "Furthermore, genes encoding proteins with critical roles in immune response, such as CD207 (Langerin) and defensin Beta 4 (DEFB4A), were significantly downregulated in periodontitis-affected tissues." (PMID 41124422, 2025).
psoriasis (1 paper, 2022). An autoimmune condition characterized by red, well-delineated plaques with silvery scales that are usually on the extensor surfaces and scalp. "We indicated that MUP attenuated IMQ-induced psoriasis-like inflammation by reducing infiltrations of CD4+T cells, CD8+T cells, Ly6G+ neutrophils in the lymphoid nodes and increasing CD207+ LCs in the epidermis." (PMID 36419191, 2022).
skin tumors (1 paper, 2025). "In line with the absolute reduction of LCs in skin tumors, a significant reduction of Cd207 and Epcam expression was observed in skin tumors." (PMID 40282557, 2025).
type 2 diabetes (1 paper, 2018). "We previously reported the increased aggregation of epidermal CD207-positive LCs and subepidermal CD68-positive macrophages in hind paw skin of db/db mice, a mouse model of type 2 diabetes, during mechanical allodynia." (PMID 29408929, 2018).
ulcer (1 paper, 2018). "Infiltration of immature CD207+/Langerin+ DCs in the peritumoral area of invasive cutaneous malignant melanoma (CMM) is correlated with increased tumor growth, a high mitotic rate, and CMM ulcer development, all leading to disease exacerbation and a worse prognosis." (PMID 29527514, 2018).
vitiligo (1 paper, 2011). Generalized well circumscribed patches of leukoderma that are generally distributed over symmetric body locations and is due to autoimmune destruction of melanocytes. "NALP-1 bearingLangerhans cells appear as orange dots in merged images, and more noticeable colocalizationof NALP-1 and CD207/Langerin were found in leading edge vitiligo skin." (PMID 21541348, 2011).
tumor (24 papers, 2012 to 2025). "The current sequencing experiment from different tumour sampling sites enabled the detection of tissue-specific cells, such as Langerhans-like dendritic cells (DC_CD207) and lipid-associated macrophages (M_MMP9) enriched in the omentum." (PMID 34238352, 2021). "It was shown that tumor-associated cDC2s possess langerin-encoding CD207 gene as a marker both in human and mouse lung tumors." (PMID 33228747, 2020). "The diagnosis of LCH is established by identifying clonal tumor proliferation, characterized by the expression of CD1a, CD207 (Langerin), and S100 proteins." (PMID 41426579, 2025). "Within the tumor and surrounding tissue, antigen-presenting cells were evident, including Langerhans cells (CD207+HLA-DR+) (BCC, 19.08% ± 2.83% [n = 11] and SCC, 7.85% ± 0.69% [n = 5]), but less than in normal skin (32.22% ± 6.89% [n = 5])." (PMID 36074574, 2022). "Fifteen distinct clusters were identified and five clusters (M_C1_PLTP, M_C3_CCL20, M_C4_CXCL10, M_C5_NBEAL1, and M_C12_CD207) were abundant in tumor." (PMID 35102420, 2022). "Immunohistochemically, the tumor cells were positive for S-100 and CD1a and weak positive for Langerin (CD207)." (PMID 35106213, 2021). "As for immunohistochemistry, all neoplasms stained positively for CD1a, CD207 (Langerin) and S100; inconstant was the stain for CD34 and CD68 (approximately 60%)." (PMID 32825016, 2020). "CD1a+ and CD207+ cells were observed throughout the epithelium, while, in the connective tissue, they were more prevalent in the tumor nests of the OSMF-OSCC and OSCC lesions." (PMID 31880289, 2020). "Cells in the tumor also stain positive for CD207, a marker for Langerhans cells (LCs), the antigen-presenting cells of the epidermis." (PMID 24116092, 2013). "The tumor cells showed intense membrane staining for CD1a, strong granular cytoplasmic staining for langerin (CD207), strong staining for S100 and CD4." (PMID 23006414, 2012). "Whether these CD207-expressing DCs found in EBV-associated tumors are similar to tCD207 DCs and what role these DCs may play in tumor biology is of great interest and remains to be further investigated." (PMID 27252701, 2016). "Depletion of CD11c+ CD207 high cells in future studies may resolve whether the influx LC cells in response to Cl-IB-MECA is sufficient for its anti-tumour effect or whether the local release of TNFα by T-cells has additional effects." (PMID 23028986, 2012). "Direct in vivo DC vaccination involves the targeted delivery of tumor antigens to DCs through the use of chimeric proteins, which will fuse tumor antigens to antibodies specific for a given DC receptor, such as CD205 or Langerin/CD207." (PMID 23606870, 2013). "Subsequently, pathological biopsy of the lymph nodes revealed high expression of CD163, CD68, S100, Lys and CD34 in the tumor cells and no expression of CD1a and CD207, confirming this rare clinical diagnosis." (PMID 36969238, 2023). "However, the expression of CLEC4A, CLEC4D, CLEC4E, CLEC4J (FCER2), CLEC4K (CD207), CLEC4G, CLEC4H1, CLEC4M, and CLEC4H2 decreased with tumor progression." (PMID 34409028, 2021). "The tumor cells expressed CD1a, Langerin (CD207), S-100 protein, CD68 and vimentin, and did not express pan-T or B cell markers and epithelial markers." (PMID 22889043, 2012). "The tumor typically shows positivity for S-100 protein and CD1a but is negative for CD207/langerin." (PMID 38713245, 2024). "Tumor cells showed diffuse positivity with CD68 and S100 immunohistochemistry, while CD1a, langerin (CD207), and BRAF p.V600E reactions were negative." (PMID 36416966, 2023). "Compared with follicular dendritic cells and Langerhans cells of the same family, tumor cells are negative for CD21, CD23, CD35, D2–40, CD207, CD1a, and CK." (PMID 33655917, 2021). "Two of these were related to a case of a heavily EBER-positive tumor with dense infiltrates of lymphocytes, making a distinction of nontumor-infiltrated surrounding stroma (CD8 and CD207 analyses) too unreliable." (PMID 33218184, 2020).
tumor (continued). "TNFR ablation in the BM did not affect numbers of dendritic cells (CD207+ CD11c+), NK or NKT cells infiltrating wounds or tumours." (PMID 25575023, 2015).
infection (13 papers, 2007 to 2024). The state of being infected such as from the introduction of a foreign agent such as serum, vaccine, antigenic substance or organism. "A particularity of the disease is involvement of polymorphisms such as in IFNAR1 and CD207 that regulate antigen-presenting cell responses to infection." (PMID 37188663, 2023). "We found that upon infection, there is an expansion of all the myeloid cells, but notably so within the Mrc1+ macrophage, Cd14+ monocyte and Cd207+ Langerhans cell subclusters." (PMID 37644007, 2023). "Infection of the grass carp (Ctenopharyngodon idella) with Flavobacterium columnare upregulated CD207 only in the spleen, suggesting that the biological function of CD207 may be related to APP." (PMID 35563287, 2022). "APCs express at least three immunoreceptors that belong to the calcium-dependent (C-type) lectin family: DC-specific intercellular adhesion molecule 3 grabbing non integrin (DC-SIGN, CD209), DEC-205 (CD205), and Langerin (CD207), which can be utilized by pathogens to initiate infection." (PMID 32391004, 2020). "The significant drops in the numbers of L/CD207+ cells in the spleen at 3 d pc suggest possible migration of these cells from the spleen to the site of infection followed by remarkable increases in LC-like numbers in the spleens of the vaccinated catfish after 7 d of the treatment." (PMID 30894864, 2019). "These seven publications indicate one fact: blockade of the interactions between the C-type lectins (CD205, CD207, CD209) and carbohydrates of bacteria inhibit bacterial interactions with the host, dissemination, and infection." (PMID 33488579, 2020). "Staining the skin sections for CD207 highlighted a lack of skin-specific DCs (Langerhans cells) post-infection with 5448AP compared to postinfection with 5448 or naive skin." (PMID 36744883, 2023). "Indeed, iDCs can mediate trans-infection through the interaction of several proteins belonging to the C-type lectin receptor (CLRs) family [such as DC-SIGN, mannose receptor (MR) (also known as CD206), langerin (CD207), and syndecan-3] with HIV-1 GP120 protein." (PMID 32181159, 2020).
cancer (7 papers, 2015 to 2025). A tumor composed of atypical neoplastic, often pleomorphic cells that invade other tissues. "In colorectal and breast cancers, the substantial enrichment of CD207+ DCs correlates with better cancer prognosis." (PMID 41430039, 2025). "CD8+ cells were present in areas of cancer cells and in the surrounding stroma, whereas CD207+ cells were observed largely in areas of cancer cells." (PMID 33218184, 2020). "For quantification of CD207+ cells, defined areas were selected representing cancer cells and surrounding stroma." (PMID 33218184, 2020). "While CD8+ cells were present in cancer cell areas and in surrounding stroma, CD207+ cells were observed largely in cancer cell areas." (PMID 33218184, 2020). "They uniquely express high levels of the C-type lectin receptor Langerin (CD207), which is an attractive target for antigen delivery in immunotherapeutic vaccination strategies against cancer." (PMID 32760719, 2020). "The frequencies of pixels representing CD207 were 0.25% (0.040–1.39) for areas of cancer cells and 0.030% (0–0.065) for surrounding stroma, representing an 8-fold difference (p < 0.0001)." (PMID 33218184, 2020). "Consistent with immunohistochemical analyses, COX-2 co-localized with CD207 (LC marker) and was present both in cancer cells and LCs." (PMID 29610553, 2018). "It was originally assumed that the neoplastic transformation responsible for cancer development in LCH occurs within CD1a+CD207+(Langerin+) LCs in the skin." (PMID 26459350, 2015). "Importantly, our present observations added the information that these cells were largely distributed within the areas of cancer cells, i.e., the frequency of CD207+ cells was 8-fold greater in this compartment cf. the surrounding stroma." (PMID 33218184, 2020). "However, while CD207+ DCs were present in close relation to cancer cells, this was apparently not enough to induce a meaningful immunological response targeting cancer antigens, which would prevent NPC from occurring or to be killed off." (PMID 33218184, 2020). "In our study, CD1a, CD207, and CD303 were selected based on previous studies investigating different malignant neoplasms and the biological behavior of such markers." (PMID 31880289, 2020). "In conclusion, NPC lesions are heterogeneous with regard to the presence and distribution of cancer cells as well as immune cells (CD8+ T-cells and CD207+ DCs)." (PMID 33218184, 2020). "CD207+ DCs express CD1a and CD207, have been detected in a variety of cancer types, encompassing non-cutaneous malignancies." (PMID 41430039, 2025). "In contrast, double staining for mPGES-1 and CD207, or for mPGES-1 and COX-2 showed that mPGES-1 co-localized with COX-2 in cancer cells, but not in LCs." (PMID 29610553, 2018).
adenocarcinoma (1 paper, 2023). A common cancer characterized by the presence of malignant glandular cells. "We also found a significantly different expression of two very important plasma proteins related to lymphocyte functions: CD207, which showed a decreased plasma concentration, and CD66a/CEACAM1, which showed higher plasma levels in the adenocarcinoma group." (PMID 37610509, 2023).
bacterial infections (1 paper, 2020). "CCVR and COCPs have previously been reported to reduced frequencies of CD207+ Langerhans cells in the vagina, which are known to activate cutaneous Th17 responses in response to bacterial infections." (PMID 31675420, 2020).
immune dysfunctions (1 paper, 2024). "Regarding immune dysfunctions, LCH lesion CD207+ DCs exhibit elevated levels of T‐cell costimulatory molecules and proinflammatory cytokines." (PMID 39190425, 2024).
CD207 also shares sentences with these, for which no sentence is quoted: histiocytic neoplasm (2 papers); leprosy (2); Allergy (1); atherosclerosis (1); breast carcinoma (1); chronic obstructive pulmonary disease (1); cryptococcosis (1); histiocytic sarcoma (1); inflammatory bowel disease (1); inflammatory skin disorders (1); leishmaniasis (1); lung adenocarcinoma (1); lung disease (1); melanoma (1); oral squamous cell carcinoma (1); oral submucous fibrosis (1); squamous cell carcinoma (1); viral infections (1).